SPRR2G (small proline rich protein 2G)
Description:
Cross-linked envelope protein of keratinocytes. It is a keratinocyte protein that first appears in the cell cytosol, but ultimately becomes cross-linked to membrane proteins by transglutaminase. All that results in the formation of an insoluble envelope beneath the plasma membrane (By similarity).
Tractability: Antibody: its Gene Ontology location is reachable by antibodies, with high confidence.
Gene: Protein-coding gene on chromosome 1 (153,149,582 to 153,150,890, reverse strand). Ensembl gene ENSG00000159516.
Subcellular location: Cytoplasm
Pathways (Reactome):
Developmental Biology: Formation of the cornified envelope
Gene Ontology:
Biological process: epidermis development; keratinocyte differentiation
Cellular component: cornified envelope; cytosol; cytoplasm
Genetic constraint (gnomAD): Loss-of-function variants: 3 observed, 2.54 expected, observed/expected ratio (o/e) 1.18, 90% interval 0.49 to 1.9. That is too few expected variants to judge how well the gene tolerates losing a copy. Missense variants: 96 observed, 92.24 expected, observed/expected ratio (o/e) 1.04, 90% interval 0.88 to 1.23. Synonymous variants: 38 observed, 36.07 expected, observed/expected ratio (o/e) 1.05, 90% interval 0.81 to 1.38.
Homologues: Orthologues: chimpanzee SPRR2G (99% identical). Paralogues in human: SPRR1A (52% identical), SPRR1B (52% identical), PRR9 (47% identical), SPRR3 (47% identical), SPRR4 (42% identical), LCE2B (30% identical), LCE2C (30% identical), LCE2D (30% identical), LCE2A (29% identical), LCE1E (27% identical), LCE1F (27% identical), LCE3D (27% identical), and 8 more.
Diseases named in the same sentence as SPRR2G in open-access papers:
SPRR2G is named in the same sentence as 12 diseases in open-access papers, as found by Europe PMC text mining. Sharing a sentence is not in itself a finding about the gene and the disease. The quoted sentences say what the papers report.
cervical cancer (1 paper, 2021). A primary or metastatic malignant neoplasm involving the cervix. "Approximately one third (7 of 19; SPRR2G, RAET1G, FOXA2, BNIPL, LOR, LCE2B, and LCE1B) had expression that was highest among the NED/Stage1/Stage2 cluster, lower in the premalignant cluster, and even lower in Stage 3 cervical cancer tissue." (PMID 34944802, 2021).
dementia (1 paper, 2024). Loss of intellectual abilities interfering with an individual's social and occupational functions. "In the case of SPRR2G, the gene is also connected to other neurological disorders such as dementia and Parkinson’s." (PMID 39766348, 2024).
medulloblastoma (1 paper, 2024). A malignant, invasive embryonal neoplasm arising from the cerebellum. "However, there is no available AD-related information for the ESPL1, KIF20A, SPRR2G, and SPRR3 genes, which instead have associations with various cancers, including adenocarcinoma, medulloblastoma, tongue cancer, and pancreatic cancer, respectively." (PMID 39766348, 2024).
SPRR2G also shares sentences with these, for which no sentence is quoted: psoriasis (2 papers); adenocarcinoma (1); cancer (1); infection (1); neurological disorders (1); pancreatic cancer (1); Parkinson’s (1); tongue cancer (1); tumor (1).